GATD1 (glutamine amidotransferase class 1 domain containing 1)
Description:
Component of the FERRY complex (Five-subunit Endosomal Rab5 and RNA/ribosome intermediary). The FERRY complex directly interacts with mRNAs and RAB5A, and functions as a RAB5A effector involved in the localization and the distribution of specific mRNAs most likely by mediating their endosomal transport. The complex recruits mRNAs and ribosomes to early endosomes through direct mRNA-interaction.
Synonyms: Fy-5; FERRY5; PDDC1; FLJ34283; FY5
Tractability: Antibody: UniProt places it where antibodies can reach, with high confidence; UniProt predicts a signal peptide or a membrane-spanning region; its Gene Ontology location is reachable by antibodies, with medium confidence. PROTAC: ubiquitination databases record sites on it.
Gene: Protein-coding gene on chromosome 11 (767,220 to 777,488, reverse strand). Ensembl gene ENSG00000177225.
Subcellular location: Secreted; Early endosome
Subcellular location (Human Protein Atlas): Nucleoplasm; Predicted to be secreted
Gene Ontology:
Molecular function: glyoxalase III activity
Biological process: regulation of intracellular mRNA localization; methylglyoxal catabolic process
Cellular component: extracellular exosome; early endosome; extracellular region
Genetic constraint (gnomAD): Loss-of-function variants: 20 observed, 19.51 expected, observed/expected ratio (o/e) 1.03, 90% interval 0.72 to 1.49. The synonymous counts are far from expectation, so gnomAD's model fits this gene poorly and the ratio says little. Missense variants: 317 observed, 271.56 expected, observed/expected ratio (o/e) 1.17, 90% interval 1.06 to 1.28. Synonymous variants: 163 observed, 117.71 expected, observed/expected ratio (o/e) 1.38, 90% interval 1.22 to 1.58.
Homologues: Orthologues: chimpanzee GATD1 (99% identical), macaque GATD1 (98% identical), mouse Gatd1 (93% identical), rat Gatd1 (92% identical), guinea pig GATD1 (92% identical), pig GATD1 (91% identical), dog GATD1 (85% identical).
Diseases named in the same sentence as GATD1 in open-access papers:
GATD1 is named in the same sentence as 4 diseases in open-access papers, as found by Europe PMC text mining. Sharing a sentence is not in itself a finding about the gene and the disease. The quoted sentences say what the papers report.
neurologic disease (1 paper, 2025). "Neurologic disorders have yet to be associated with mutation of GATD1 or CRYZL1." (PMID 40062705, 2025). "Mutation of the remaining two members of the FERRY complex, glutamine amidotransferase-like class 1 domain containing 1 (GATD1) and crystallin, zeta (quinone reductase)-like 1 (CRYZL1) has not yet been associated with neurologic disease." (PMID 40062705, 2025).
GATD1 also shares sentences with these, for which no sentence is quoted: cancer (1 paper); COVID-19 (1); keratoconus (1).